ALS2 (alsin Rho guanine nucleotide exchange factor ALS2)
Diseases named in the same sentence as ALS2 in open-access papers (continued):
Sharing a sentence is not in itself a finding about the gene and the disease.
cancer (2 papers, 2020 to 2022). A tumor composed of atypical neoplastic, often pleomorphic cells that invade other tissues. "Collectively, these data indicate that ALS2 expression generally coincides with the presence of HIF-1α, but that ALS2 upregulation is associated with poor prognosis in a subgroup of cancers." (PMID 33339852, 2020). "Here, we identified ALS2, a guanine nucleotide exchange factor that is upregulated in cancer, as responsible for increased Rab5-GTP loading, cell migration and metastasis in hypoxia." (PMID 33339852, 2020). "Importantly, increased ALS2 expression correlates with augmented HIF-1α levels in cancer biopsies, making it a promising marker for the detection of HIF-1α and hypoxia-related cancers." (PMID 33339852, 2020). "Interestingly, six genes, including ALS2, DAPL1, HS6ST1, IGFBP2, MGC12982, PPIAL4C, are selected in all predictions, i.e., when no samples is removed, or one cancer type data is removed." (PMID 35349572, 2022).
infection (2 papers, 2011 to 2025). The state of being infected such as from the introduction of a foreign agent such as serum, vaccine, antigenic substance or organism. "Some of the genes encoding cell-surface proteins such as ALS2, ALS9 which are known to be expressed during infection were also found to be downregulated while ALS6/ALS7 appear to be upregulated." (PMID 22114559, 2011).
neurodegenerative disease (2 papers, 2013 to 2022). A disorder of the central nervous system characterized by gradual and progressive loss of neural tissue and neurologic function. "Other human neurodegenerative disease-related genes sharing a PH/RhoGEF domain, such as DNM2, SBF2, and ALS2, could provide important clues for these elusive questions." (PMID 23844677, 2013).
tumor (2 papers, 2014 to 2020). "In conclusion, this study uncovers the Rab5GEF ALS2 as a novel hypoxia inducible target gene that is associated with augmented tumor cell migration, invasion and metastasis." (PMID 33339852, 2020). "Hence, this study identifies ALS2 as a novel hypoxia-inducible gene associated with tumor progression and metastasis." (PMID 33339852, 2020). "Strikingly, ALS2 upregulation in hypoxia was required for Rab5 activation, tumor cell migration and invasion, as well as experimental metastasis in C57BL/6 mice." (PMID 33339852, 2020). "Another challenging possibility that emerges from these observations is the potential link between hypoxia and tumor cell viability via ALS2-dependent activation of “a salvage pathway”." (PMID 33339852, 2020). "Taken together, these data indicate that ALS2 contributes to tumor cell invasion and experimental metastasis induced by hypoxia." (PMID 33339852, 2020). "Remarkably, although ALS2 was detected in both non-tumor and CCRCC samples, levels of ALS2 were substantially higher in the tumors." (PMID 33339852, 2020). "Hence, the identification of the Rab5GEF ALS2 as a HIF-1α target gene prompted us to evaluate the impact of ALS2 induction in tumor cell migration, invasion and metastasis." (PMID 33339852, 2020). "Next, we evaluated whether the effects of ALS2 in cell migration induced by hypoxia translated into responses that contribute to tumor cell invasiveness and metastasis in vivo." (PMID 33339852, 2020). "It is thus tempting to speculate that ALS2 induction in hypoxia may constitute a novel “salvage pathway” in tumor cells exposed to hypoxia." (PMID 33339852, 2020). "Therefore, the possibility that ALS2 modulates tumor cell migration via activation of Rab5 was attractive." (PMID 33339852, 2020). "Here, we identified the Rab5GEF ALS2 as a novel HIF-1α target that accounts for increased Rab5-GTP loading, tumor cell migration and invasion in hypoxia." (PMID 33339852, 2020). "This study identifies a novel hypoxia-inducible target gene, ALS2, which is overexpressed in a HIF-1α-related malignancy and promotes the acquisition of aggressive traits in tumor cells." (PMID 33339852, 2020). "In fact, ALS2 levels fluctuated within the same biopsies, where high ALS2 detection was observed within the tumor area, but not in the normal adjacent region." (PMID 33339852, 2020). "Upregulation of ALS2 in hypoxia accounted for increased Rab5-GTP loading, thereby leading to the activation of downstream pathways, that depend on hypoxia and are involved in tumor cell migration, invasion and experimental metastasis (proposed model)." (PMID 33339852, 2020).
ALS2 also shares sentences with these, for which no sentence is quoted: frontotemporal dementia (4 papers); dementia (3); neurological disease (2); Parkinson disease (2); adrenocortical carcinoma (1); Alzheimer disease (1); amyotrophic lateral sclerosis 2 (1); cognitive decline (1); dyslexia (1); generalized dystonia (1); Juvenile onset (1); leukemia (1); Lewy body dementia (1); lung squamous cell carcinoma (1); lymphoma (1); muscular dystrophies (1); neurodevelopmental disorder (1); papillary renal cell carcinoma (1); Parkinsonism (1); periodontal disease (1); sarcoma (1); schizophrenia (1); Spasticity (1).